IL22 (interleukin 22)
Diseases named in the same sentence as IL22 in open-access papers (continued):
Sharing a sentence is not in itself a finding about the gene and the disease.
kidney disease (7 papers, 2015 to 2022). "Considerable data has connected the functions of IL-22 to the pathophysiology underlying the most common kidney diseases." (PMID 35432360, 2022). "Upon the protective and pathogenic roles of IL-22 in the kidney, the application of IL-22 in the treatment of renal diseases can be attempted." (PMID 35432360, 2022). "And IL-22, the most marked cytokine of Th17 cells, had the possibility of being involved in their pathogenic role in renal disease." (PMID 35432360, 2022). "Our understanding of the mechanistic link between IL-22 and kidney disease has improved dramatically in recent years." (PMID 35432360, 2022). "We will also propose the possibility of targeting IL-22 and its related signaling pathways in the treatment of kidney diseases." (PMID 35432360, 2022). "In the treatment of renal diseases, the application of enhancing or attenuating IL-22 effects should be determined according to the specific microenvironment." (PMID 35432360, 2022). "IL-22 is essential in promoting the regeneration of renal tissue and defending against pathogens, but aberrant activation of IL-22 promotes the pathogenesis of various renal diseases." (PMID 35432360, 2022). "Taken together, our findings unravel new mechanistic insights into protective effects of IL‐22 on kidneys and highlight the therapeutic opportunities of IL‐22 and the involved metabolic regulators in various kidney diseases." (PMID 33634980, 2021). "Further research on IL-22 biology will undoubtedly contribute to a better understanding of many kidney diseases and potential therapeutic approaches, opening the way for the identification of new therapeutic approaches and directions for the application in the clinic." (PMID 35432360, 2022). "Also, we summarize the latest progress in understanding the physiological and pathological effects of IL-22 in the kidney, suggesting the potential strategies for the specific application of this cytokine in the treatment of kidney disease." (PMID 35432360, 2022). "Whether IL-22 is protective or destructive in kidney diseases may depend on different microenvironment." (PMID 32338120, 2020). "IL-22 has been intensively reported to play a critical role in various kidney diseases." (PMID 31616439, 2019). "Although mounting evidence implicated the renoprotective potential of IL-22 in various kidney diseases, the role of IL-22 in AAN has never been described." (PMID 31616439, 2019). "However, it remains controversial whether IL-22 exerted pro-fibrotic or anti-fibrotic effects in renal diseases as well as other fibrotic disorders." (PMID 31616439, 2019). "Moreover, by reducing interleukin-22 production, ES-62 may desensitize downstream effector mechanisms in the pathogenesis of kidney disease." (PMID 25546822, 2015). "Currently, no drugs that directly target IL-22 have been approved by the FDA for the treatment of kidney disease." (PMID 35432360, 2022). "Although these studies demonstrate the roles of IL-22 in protection of kidney diseases, up to now, the effects and mechanisms of IL-22 in renal TIF have not been confirmed." (PMID 32338120, 2020).
gastrointestinal disease (6 papers, 2015 to 2024). A disease that occurs in the gastrointestinal system, excluding the hepatobiliary system. "IL-22 has been proposed as a promising therapeutic target in treating many gastrointestinal diseases." (PMID 37908362, 2023). "The AhR pathway is accompanied by a decrease in glucagon-like peptide-1 (GLP-1) and Interleukin-22 (IL-22), resulting in changes in the intestinal permeability and lipopolysaccharide in functional gastrointestinal diseases." (PMID 34631603, 2021). "IL-22 is the most intensively studied cytokine within this family in contexts of gastrointestinal disease, but the importance of other family members is more and more appreciated." (PMID 29967613, 2018). "Our continued study of these molecules can aid in the understanding IL-22, particularly in the setting of gastrointestinal disease." (PMID 26793707, 2015). "Notably, a correlation was identified between specific clinical characteristics (e.g., CA125, CA199, Glu, CKMB and IL-22) and gut microbiota among patients with gastrointestinal diseases." (PMID 38751718, 2024). "Additionally, a discernible correlation was established between certain clinical characteristics, including CA125, CA199, IL-22, among others and gut microbiota among patients with gastrointestinal diseases." (PMID 38751718, 2024). "Furthermore, the studies described in this review highlight IL-22 as a potential and promising therapeutic target for many gastrointestinal diseases." (PMID 26793707, 2015). "In addition, this article describes the roles of IL-22 in the pathogenesis of several gastrointestinal diseases, including inhibition of inflammation and barrier defense against pathogens within the intestine." (PMID 26793707, 2015).
neurological disease (6 papers, 2014 to 2023). "IL-22 deficiency lessened weight loss, moderated the systemic inflammatory response, and greatly improved clinical signs of neurological disease and mortality." (PMID 32843067, 2020). "We found increased animal survival, improved clinical signs of neurological disease, and reduced viral burden in the IL-22-/- neonatal mice." (PMID 32843067, 2020). "We also demonstrate that even if the IL-22/IL-22R1 couple is present in the brain of control patients with other neurological disease than MS, it nevertheless predominates in the brain of MS patients, in particular in the plaques." (PMID 26077779, 2015). "In contrast, the ratios between IL-22 and IL-6 or IL-8 were not appropriated to discriminate the risk for neurological disease." (PMID 33776990, 2021). "The proportion between IL-22 and TNF serum levels was also able to discriminate neurological disease (9.2 vs 3.0, P = 0.025) from non-neurological disease during acute phase." (PMID 33776990, 2021).
neurodegenerative disease (4 papers, 2022 to 2025). A disorder of the central nervous system characterized by gradual and progressive loss of neural tissue and neurologic function. "IL-22, a member of the IL-10 family, is involved in the proinflammatory response, tissue injury, and repair and is associated with neurodegenerative diseases." (PMID 40431417, 2025). "A separate investigation has documented that elevated levels of IL-22 play a role in the pathogenesis of neurodegenerative diseases." (PMID 38002479, 2023).
colon (3 papers, 2018 to 2024). "The enhanced IL-22 activity is important to promote wound healing; however, the prolonged IL-22 production and activity during the recovery phase promoted colon cancerogenesis, thus showing a link between inflammation/wound healing and colon tumorigenesis." (PMID 29652830, 2018).
neurodevelopmental disorder (2 papers, 2023 to 2024). A behavioral and cognitive disorder with onset during the developmental period that involves impaired or aberrant development of intellectual, motor, or social functions. "The cytokine IL-22 is essential in beginning an inflammatory response and so contributes to the inflammation seen in neurodevelopmental disorders." (PMID 38003408, 2023).
urinary tract disease (2 papers, 2014 to 2020). "Thus, the described explant technique is clearly capable of generating functional HUCs suitable for the study of human urinary tract disorders, including interactions between urothelium and IL22-producing cells." (PMID 25354343, 2014).
connective tissue diseases (1 paper, 2021). "It has recently been reported that IL-22 also contributes to the pathogenesis of many connective tissue diseases (CTDs)." (PMID 33407883, 2021).
gastrointestinal disorders (1 paper, 2024). "Activation of the AhR pathway correlates with reduced levels of glucagon-like peptide-1 (GLP-1) and interleukin-22 (IL-22), subsequently influencing intestinal permeability and lipopolysaccharide levels in functional gastrointestinal disorders." (PMID 39200318, 2024).
hematological malignancies (1 paper, 2015). "Recent studies have implicated the role of Th22 and IL-22 in the pathogenesis of a variety of solid tumors and a limited number of hematological malignancies including AML, MDS and ALL." (PMID 26000313, 2015).
IL22 also shares sentences with these, for which no sentence is quoted: ankylosing spondylitis (8 papers); spondyloarthritis (5); acute myocardial infarction (4); Cognitive impairment (4); mantle cell lymphoma (4); nonalcoholic steatohepatitis (4); unstable angina (4); autoimmune polyglandular syndromes (3); heart failure (3); meningitis (3); myasthenia gravis (3); portal hypertension (3); Thrombocytopenia (3); acute-on-chronic liver failure (2); aseptic meningitis (2); Atrophy (2); cholera (2); colorectal adenocarcinoma (2); dermatomyositis (2); dilated cardiomyopathy (2); endocrine diseases (2); eosinophilic esophagitis (2); gastroesophageal reflux disease (2); Genetic obesity (2); H. pylori (2); hepatorenal syndrome (2); Hypercholesterolemia (2); IgA nephropathy (2); inflammatory myopathies (2); Primary Sclerosing Cholangitis (2).
A further 95 diseases each share a sentence with IL22 in 2 papers or fewer.